ARNT2 (aryl hydrocarbon receptor nuclear translocator 2)
Description:
Transcription factor that plays a role in the development of the hypothalamo-pituitary axis, postnatal brain growth, and visual and renal function. Specifically recognizes the xenobiotic response element (XRE).
Synonyms: bHLHe1; KIAA0307; WEDAS
Tractability: PROTAC: ubiquitination databases record sites on it; its protein half-life has been measured.
Gene: Protein-coding gene on chromosome 15 (80,404,315 to 80,597,937, forward strand). Ensembl gene ENSG00000172379.
Subcellular location: Nucleus
Subcellular location (Human Protein Atlas): Nucleoplasm
Pathways (Reactome):
Metabolism: Aryl hydrocarbon receptor signalling; Endogenous sterols; PPARA activates gene expression; Phase I - Functionalization of compounds; Xenobiotics
Gene expression (Transcription): NPAS4 regulates expression of target genes
Gene Ontology:
Molecular function: DNA-binding transcription factor activity, RNA polymerase II-specific; protein binding; protein heterodimerization activity; sequence-specific double-stranded DNA binding; aryl hydrocarbon receptor binding; DNA-binding transcription activator activity, RNA polymerase II-specific; DNA-binding transcription factor activity; RNA polymerase II cis-regulatory region sequence-specific DNA binding; protein dimerization activity; protein-containing complex binding
Biological process: brain development; positive regulation of transcription by RNA polymerase II; regulation of DNA-templated transcription; response to hypoxia; central nervous system development; in utero embryonic development; positive regulation of DNA-templated transcription; regulation of transcription by RNA polymerase II; xenobiotic metabolic process; negative regulation of apoptotic process; positive regulation of cell population proliferation; response to estradiol
Cellular component: nucleoplasm; nucleus; aryl hydrocarbon receptor complex; chromatin; cytoplasm; transcription regulator complex
Genetic constraint (gnomAD): Loss-of-function variants: 36 observed, 95.42 expected, observed/expected ratio (o/e) 0.38, 90% interval 0.29 to 0.5. The upper end of that interval is the gene's LOEUF score, 0.5, which puts it in group 2 of 6, group 1 being the genes least tolerant of losing a copy. Missense variants: 775 observed, 976.04 expected, observed/expected ratio (o/e) 0.79, 90% interval 0.75 to 0.84. Synonymous variants: 365 observed, 362.38 expected, observed/expected ratio (o/e) 1.01, 90% interval 0.92 to 1.1.
Homologues: Orthologues: pig ARNT2 (99% identical), macaque ARNT2 (99% identical), mouse Arnt2 (97% identical), guinea pig ARNT2 (97% identical), rat Arnt2 (97% identical), dog ARNT2 (95% identical), rabbit ARNT2 (91% identical), tropical clawed frog arnt2 (87% identical), zebrafish arnt2 (86% identical), chimpanzee ARNT2 (84% identical), Drosophila melanogaster tgo (43% identical), Caenorhabditis elegans aha-1 (31% identical), and 3 more. Paralogues in human: ARNT (65% identical), BMAL1 (27% identical), BMAL2 (26% identical), CLOCK (21% identical), NPAS2 (19% identical), PASD1 (8% identical).
Diseases named in the same sentence as ARNT2 in open-access papers:
ARNT2 is named in the same sentence as 67 diseases in open-access papers, as found by Europe PMC text mining. Sharing a sentence is not in itself a finding about the gene and the disease. The quoted sentences say what the papers report.
breast carcinoma (8 papers, 2012 to 2025). "Similar to GBM, ARNT2 expression is also lower in human breast cancer tissues, and that overexpression of ARNT2 inhibits breast cancer cell proliferation, migration, and invasion in vitro and tumor growth and metastasis in vivo." (PMID 39184078, 2024). "ARNT2 is a putative tumor suppressor in gastric cancer, hepatocellular carcinoma, oral squamous cell carcinoma, and breast cancer." (PMID 34249704, 2021). "It is well documented that xenoestrogens can downregulate aryl-hydrocarbon receptor nuclear translocator 2 (ARNT2) mRNA expression in human breast cancer cells through an ERα-dependent mechanism." (PMID 30120713, 2019). "ARNT2 was highly expressed in luminal breast cancer tissues." (PMID 34249704, 2021). "Our previous study has reported that downregulation of ARNT2 expression can affect HIF signaling and metabolism in human breast cancer cells." (PMID 23285176, 2012). "“ARNT2” is also known to have significant roles in many cancers like NSCLC, breast cancer, etc." (PMID 28148240, 2017).
glioblastoma (8 papers, 2018 to 2025). The most malignant astrocytic tumor (WHO grade IV). "To better understand the importance of ARNT2 loss in glioblastoma physiology, we performed orthotopic engraftment of empty vector and ARNT2-expressing GBM9 cells into the brain of NOD scid mice." (PMID 39184078, 2024). "Examination of tumor patients’ transcriptome datasets further associated ARNT2 with a tumorigenic/stem signature of glioblastoma cells at both the tissue and single cell levels." (PMID 29149419, 2018). "Our results demonstrate that ARNT2 controls the expression of several transcription factors associated with the stem-like properties of glioblastoma cells, and is essential for full tumorigenicity of glioblastoma cells." (PMID 29149419, 2018). "Notably, they have demonstrated that ARNT2 controls the expression of several transcription factors associated with the stem-like properties of glioblastoma cells and is essential for full tumorigenicity of glioblastoma cells." (PMID 32411235, 2020). "For example, in glioblastoma, ARNT2 has been shown to be highly expressed in proliferative subpopulations and to promote tumorigenicity through the regulation of key transcription factors such as SOX9, POU3F2 (BRN2), and OLIG2." (PMID 40723431, 2025). "Several studies have shown that ARNT2 is involved in the carcinogenesis of certain cancer types, such as non-small cell lung cancer, hepatocellular carcinoma, and glioblastoma." (PMID 39944136, 2025). "Our findings provide new insights into the complex mechanisms used by oncogenes to limit differentiation in cancer cells and define ARNT2 as a tumor suppressor in glioblastoma." (PMID 39184078, 2024). "Mechanistically, ARNT2 depletion diminishes differentiation and enhances stemness of glioblastoma cells." (PMID 39184078, 2024). "Conversely, ARNT2 overexpression severely dampens the growth of fully transformed glioblastoma cells subcutaneously or orthotopically xenografted in mice." (PMID 39184078, 2024). "ARNT2 was pointed out as a key TF in the control of glioblastoma cell aggressiveness by regulating the expression of TFs related to a tumorigenic/stem glioblastoma signature." (PMID 33924679, 2021). "Immunohistochemistry confirmed ARNT2 expression in cell sub-populations within proliferative zones of patients’ glioblastoma." (PMID 29149419, 2018). "Most importantly, our results pinpointed a previously unsuspected involvement of the hypoxia-inducing factor (HIF) family member aryl hydrocarbon receptor nuclear translocator 2 (ARNT2) in the control of glioblastoma cell aggressiveness." (PMID 29149419, 2018). "This was confirmed at the protein level by immunohistochemistry of ARNT2 expression in sub-populations of cells within proliferative zones of patients’ glioblastoma." (PMID 29149419, 2018). "We first analyzed ARNT2 expression in two published independent transcriptome datasets of glioblastoma cells either devoid of or endowed with tumor-initiating properties." (PMID 29149419, 2018). "Coherent with the profile of ARNT2 mRNA distribution across glioblastoma areas, immunohistochemical analysis of neurosurgical samples of patient’s tumors revealed enrichment in ARNT2-expressing cells with increased distance from necrosis (Online Resource 9B)." (PMID 29149419, 2018). "Further, they show that ARNT2 is part of a tumorigenic/stem signature of glioblastoma cells, and regulates the expression of transcription factors previously shown to be involved in the control of glioblastoma cell tumorigenicity." (PMID 29149419, 2018). "Taken together, these results show that ARNT2 participates in the control of the tumorigenicity of glioblastoma cells." (PMID 29149419, 2018). "We found that ARNT2 knockdown decreased the expression of SOX9, POU3F2 and OLIG2, transcription factors implicated in glioblastoma cell tumorigenicity, and repressed glioblastoma stem-like cell tumorigenic properties in vivo." (PMID 29149419, 2018).
glioblastoma (continued). "Taken together, these results demonstrate that ARNT2 is expressed at the mRNA and protein level within the tumors of patients with glioblastoma." (PMID 29149419, 2018). "Our results reveal ARNT2 as a pivotal component of the glioblastoma cell tumorigenic signature, located at a node of a transcription factor network controlling glioblastoma cell aggressiveness." (PMID 29149419, 2018). "Given the shared neuroectodermal origin of glioblastoma and melanocytes, one study raises the possibility that ARNT2 may influence melanocyte biology and pigmentation through similar developmental or stress-responsive pathways." (PMID 40723431, 2025). "Notably, ARNT2, highly and specifically expressed in the central nervous system, is diminished in glioblastoma, inversely correlating with patient survival." (PMID 39184078, 2024). "Given this distinct expression pattern of ARNT2 in normal brain and cerebellum, coupled with bioinformatics analyses indicating its reduced presence in glioblastoma, we directed our investigations towards understanding the role and regulation of ARNT2 in glioblastoma." (PMID 39184078, 2024). "Whether ARNT2 should have a similar role in CPC, miR-935 could also be modulating apoptosis sensitivity through ARNT2 downregulation; in glioblastoma, ARNT2 plays a central role in regulating stem-like cell tumorigenic properties in vivo." (PMID 37759522, 2023). "Furthermore, we demonstrated that ARNT2 knockdown inhibits tumor-initiating properties in vivo, supporting a role of ARNT2 in the tumorigenicity of glioblastoma cells." (PMID 29149419, 2018). "Analysis of the TCGA glioblastoma dataset and the French glioma dataset gse16011, showed no variation in ARNT2 expression according to MGMT status, IDH1 mutation or EGFR amplification (not shown)." (PMID 29149419, 2018). "To further explore the relevance of ARNT2 expression in the context of the human tumors, we compared its expression in the tumor core areas of glioblastomas (IVY dataset) with the expression of genes associated with glioblastoma cells endowed with tumorigenic and stem-like properties." (PMID 29149419, 2018). "Utilizing in vitro and in vivo models, we demonstrate that ARNT2 knockout (KO) exerts no discernible effect on the in vitro proliferation of glioblastoma cells, but significantly enhances the growth of glioblastoma cells in vivo." (PMID 39184078, 2024). "We found that ARNT2 knockdown not only impaired the cell tumorigenicity in vivo but also resulted in decreased expression of SOX9, POU3F2 and OLIG2, hence placing ARNT2 at the core of transcriptional regulations of glioblastoma cell tumorigenicity." (PMID 29149419, 2018). "We found that the profile of ARNT2 expression in glioblastoma does not correspond with that expected for a hypoxia-related molecule." (PMID 29149419, 2018). "Further, the analysis of the TCGA transcriptome dataset of 481 surgical tissue samples of untreated primary glioblastoma using the GlioVis Platform showed lower ARNT2 mRNA levels in glioblastoma tissues than in non-tumoral brain tissues (Online Resource 8A)." (PMID 29149419, 2018). "ARNT2 expression was highest in glioblastoma core zones rather than in the hypoxic necrotic and pseudopalisading zones." (PMID 29149419, 2018). "In glioblastoma HIF1 and 2α, but not ARNT2, have been associated to adaptation of cancer cells to hypoxic conditions." (PMID 29149419, 2018). "Decreased ARNT2 expression was consistently observed in non-tumorigenic glioblastoma cells, compared to tumorigenic cells." (PMID 29149419, 2018). "However, the previous research on the role of ARNT2 in different cancers was not consistent: ARNT2 was considered as an important tumorigenic factor in glioblastoma, and it significantly upregulated in PM2.5-induced lung cancer." (PMID 36203533, 2022).
hepatocellular carcinoma (7 papers, 2016 to 2025). A malignant tumor that arises from hepatocytes. "In lung and hepatocellular cancer patients, high levels of ARNT2 expression were positively correlated with overall survival (OS), suggesting its potential as an independent prognostic factor for OS." (PMID 37958512, 2023). "ARNT2 downregulation was observed in several cancers, i.e., hepatocellular carcinoma, oral squamous cell carcinoma, and lung cancer." (PMID 37958512, 2023). "Interestingly, GALNT12, DDT, and ARNT2 have been found to be over-represented in cancer, including colorectal cancer among others, with ARNT2 showing promoter hypermethylation in hepatoma cells." (PMID 33266012, 2020). "In murine Hepa-1 hepatoma cells it was shown that ARNT and ARNT2 dimerize equally with the AHR in the presence of TCDD and that ARNT2 outcompetes ARNT for binding to the AHR when expressed in excess." (PMID 37696456, 2023).
Obesity (7 papers, 2018 to 2026). Accumulation of substantial excess body fat. "Among these TFs, ARNT2 has been demonstrated to be associated with the prevention of obesity and obesity-related diseases." (PMID 32973568, 2020). "D707H had a moderate impact on transcriptional activity with ARNT1 and ARNT2 and was associated with obesity." (PMID 32932609, 2020). "Variant T46R shows severe loss of activity in reporter assays with both the ubiquitous ARNT1 and neuron-enriched ARNT2, and is associated with obesity, though patients lack other PWL symptoms." (PMID 32932609, 2020). "Here, we describe mice bearing a mutation in Arnt2 (R74C), which developed hyperphagic obesity as well as fatty liver and glucose intolerance." (PMID 30563851, 2018). "Similarly, G715V had a moderate impact on activity with ARNT1 and ARNT2 and was associated with obesity in at least two unrelated patients." (PMID 32932609, 2020). "A mutation in Arnt2 caused obesity by regulating food intake." (PMID 30563851, 2018). "As a consequence of hyperphagic obesity, Arnt2 mutant mice develop diabetes, insulin resistance and hepatic steatosis." (PMID 30563851, 2018). "In fact, several studies have identified obesity-associated missense variants in the SIM1 bHLH (Thr46Arg, Glu62Lys), and PAS (Ser71Arg, Ile128Thr, Gln152Glu, Arg171His, Leu238Arg) domains, all of which are involved in forming the heterodimer with ARNT2." (PMID 41516406, 2026). "ARNT2 is part of the hypoxia-inducible factor (HIF) pathway, which has a role in the progression of obesity and metabolic disease." (PMID 33988505, 2021). "As ARNT2 is enriched in neurons, and Arnt2−/− mice phenocopy the loss of PVH neurons observed in Sim1−/− mice, it is hypothesized that disruption of the SIM1/ARNT2 axis drives obesity in humans with or without clinical features that are also described in Prader-Willi-like (PWL) syndrome." (PMID 32932609, 2020).
lung cancer (5 papers, 2017 to 2023). A malignant neoplasm involving the lung. "Finally, both cell lines overexpress Arnt2, which has been previously associated to lung cancer." (PMID 34870316, 2022). "ARNT2 expression is significantly lower in nonsmall cell lung cancer (NSCLC) compared to normal tissues." (PMID 28904855, 2017).
autism (4 papers, 2012 to 2024). Persistent deficits in social interaction and communication and interaction as well as a markedly restricted repertoire of activity and interest as well as repetitive patterns of behavior. "In humans, larger association studies of ARNT2 SNPs with endophenotypes linked to autism will be particularly relevant." (PMID 25745553, 2015). "A genetic association has been found between the ARNT2 gene and both autism and Asperger syndrome." (PMID 23241247, 2012). "We identified 710 SNPs in these lines that indicate new potentially important genes for FP such as TMPRSS6 (implicated in autism), and SST and ARNT2 (somatostatin function)." (PMID 39702044, 2024). "Future work in animals should employ well-designed behavioural assays relevant to autism in Arnt2 knockout mice, such as social-preference paradigms." (PMID 25745553, 2015). "Interestingly, in a genetic association study, Chakrabarti and colleagues identified variations in the ARNT2 gene, ESR1, ESR2 and also CYP19A1 to be associated with ASC diagnosis and/or autism traits in the general population." (PMID 26066795, 2015).
colorectal cancer (3 papers, 2020 to 2024). A primary or metastatic malignant neoplasm that affects the colon or rectum. "For example, ARNT2 is upregulated in human colorectal cancer (CRC), and that knockdown of ARNT2 inhibits CRC cell proliferation and invasion in vitro as well as tumor growth and metastasis through the activation of the Wnt/β-catenin signaling pathway." (PMID 39184078, 2024).
glioma (3 papers, 2018 to 2024). A benign or malignant brain and spinal cord tumor that arises from glial cells (astrocytes, oligodendrocytes, ependymal cells). "Among genes downregulated upon ARNT2 KO, some were repressed in the higher glioma grades, likely resulting in better patient prognosis." (PMID 39184078, 2024). "We demonstrated that ARNT2 expression, which is exclusively confined to the central nervous system, is lost in high-grade glioma." (PMID 39184078, 2024). "Similar to ARNT2, lower expression of these genes correlated with shorter survival of glioma patients." (PMID 39184078, 2024). "Among the genes upregulated upon ARNT2 knockout (KO), some exhibit increased expression levels with higher glioma grades, which also correlate with poorer patient survival." (PMID 39184078, 2024). "TCGA data revealed a decrease in ARNT2 levels with higher glioma grades, a trend corroborated by analysis of the Chinese Glioma Genome Atlas (CGGA)." (PMID 39184078, 2024).
colon adenocarcinoma (2 papers, 2024). "In contrast, ARNT2 levels were repressed in colon adenocarcinoma (COAD), kidney renal clear cell carcinoma (KIRC), and most importantly, GBM." (PMID 39184078, 2024).
developmental delay (2 papers, 2012 to 2021). "A previous report showed that a homozygous frameshift in ARNT2 causes visual anomalies and various developmental delays in children from a highly consanguineous family." (PMID 33435129, 2021). "It is known that ARNT2 is located on 15q24-25, while 15q24 microdeletion syndrome has been recently described as a recurrent, submicroscopic genomic imbalance found in individuals with developmental delay, craniofacial dysmorphism, digital and genital abnormalities (including HS)." (PMID 23285176, 2012).
Hepatic steatosis (2 papers, 2018 to 2020). Steatosis is a term used to denote lipid accumulation within hepatocytes. "Studies have shown that ARNT2 is necessary for the production of secretory hormones, and an induced missense mutation in ARNT2 developed hepatic steatosis and abnormalities in glucose homeostasis." (PMID 32973568, 2020).
ischemia (2 papers, 2014 to 2018). A hypoperfusion of the BLOOD through an organ or tissue caused by a PATHOLOGIC CONSTRICTION or obstruction of its BLOOD VESSELS, or an absence of BLOOD CIRCULATION. "The aryl-hydrocarbon receptor nuclear translocator 2 (ARNT2) protein has been associated with neuroprotection in models of ischemia and neuronal responses to stressors." (PMID 30231889, 2018). "Notably, lack of NPAS4 and/or BDNF expression has been linked to neurodegenerative diseases and worsened disease stroke/ischemia models and reductions of both Npas4 and Arnt2 mRNA have been observed in a rat model of depression." (PMID 30231889, 2018). "NPAS4 combines with ARNT2 to regulate the expression of BDNF, with consequent neuroprotective effects on brain injury and ischemia." (PMID 24669275, 2014).